BAG3 (BAG cochaperone 3)
Diseases named in the same sentence as BAG3 in open-access papers (continued):
Sharing a sentence is not in itself a finding about the gene and the disease.
heart failure (33 papers, 2014 to 2026). Inability of the heart to pump blood at an adequate rate to meet tissue metabolic requirements. "To extend the validity of our findings in vitro, we generated an snRNA-Seq dataset from heart failure patients harboring BAG3 mutations." (PMID 39744939, 2025). "For instance, F Dominguez described how a form of dilated cardiomyopathy (DCM), caused by mutations in BAG3, is more likely to lead to progressive heart failure in individuals over 40 years old." (PMID 38540729, 2024). "Decreased expression of BAG3 in the heart is associated with contractile dysfunction and heart failure." (PMID 34011988, 2021). "We find that antisense-mediated knockdown of Bag3 in zebrafish embryos causes heart failure and myopathy." (PMID 33137814, 2020). "The myogenic differentiation of bag3-deficient mice seems to proceed normally and thus it is assumed that the early lethality of these mice originates from respiratory and heart failure." (PMID 28680391, 2017). "That BAG3 plays an important role in the progression of heart failure is demonstrated by the finding that loss of function mutations result in the development of both early-onset and late-onset familial dilated cardiomyopathy." (PMID 25925243, 2015). "The importance of BAG3 in the homeostasis of myocytes and its role in the development of heart failure was evidenced by the finding that single allelic mutations in BAG3 were associated with familial dilated cardiomyopathy." (PMID 25925243, 2015). "Various pathogenic BAG3 variants are associated with a high risk for heart failure progression." (PMID 41250780, 2025). "Finally, increasing BAG3 using adeno-associated virus gene therapy in mice with heart failure restores myofilament Fmax and sarcomere protein turnover." (PMID 34011988, 2021). "Furthermore, all subjects with BAG3 mutations who had acute onset of heart failure following viral-like illness had very low LVEF (10-22%), that is consistent with poor response to any pathogen-related stress." (PMID 25008357, 2014). "Moreover, all severely affected BAG3 mutation carriers of the DCM-18 family had disease onset related to the influenza of 1988 along with two of deceased first-degree members of the family who developed progressive heart failure leading to death." (PMID 25008357, 2014). "Our findings associate BAG3 with left ventricular EDV, ESV, and EF, potentially supporting its role in cardiac function and heart failure pathogenesis." (PMID 41172738, 2025). "Decreased cardiac expression of BAG3 is correlated with contractile dysfunction and heart failure, decreased BAG3-dependent sarcomere protein turnover impairs mechanical function, and sarcomere force-generating capacity is restored with BAG3 gene therapy." (PMID 39684673, 2024). "In these mice with heart failure with reduced ejection fraction (HFrEF), the decrease in BAG3 directly correlated with a decline in Fmax." (PMID 36980278, 2023). "Ec-HSP70 and BAG3 are identified as independent prognostic markers of mortality with heart failure and cardiac arrest." (PMID 37371652, 2023). "Our findings indicate that impaired sarcomere protein turnover contributes to decreased Fmax in heart failure and highlight BAG3 as an essential factor for sarcomere functional maintenance." (PMID 34011988, 2021). "An earlier study had shown that BAG3 gene therapy restored in vivo cardiac function in a mouse model of heart failure secondary to coronary artery ligation." (PMID 34011988, 2021).
heart failure (continued). "Whereas morpholino-mediated ablation of Bag3 in zebrafish embryos led to severe heart failure and myopathic phenotypes, the knockout of Bag3 by CRISPR/Cas9 technology was not accompanied by phenotypic alterations in the developing embryo." (PMID 33137814, 2020). "Observations from experimental data are inconclusive and limited; one BAG3 knockdown zebrafish model observed variable phenotypes including heart failure and a skeletal myopathy." (PMID 32927679, 2020). "Of note, BAG3-related DCM is associated with a late onset, severe progressive heart failure (HF) phenotype, worse outcomes in individuals of African ancestry and a higher likelihood of terminal DCM requiring cardiac transplantation." (PMID 32927679, 2020). "As part of the mechanism induced to prevent heart failure and ischemia/reperfusion damage, BAG3 promotes cell survival through binding to several proteins including hsp70 and Bcl2." (PMID 30792263, 2019). "Due to the possibility of detection in the serum of patients, BAG3 is discussed as a suitable prognostic factor for heart failure." (PMID 28680391, 2017). "Recently, elevated concentrations of a soluble form of BAG3 were described in patients affected by advanced stage of heart failure (HF), identifying BAG3 as a potentially useful biomarker in monitoring HF progression." (PMID 27763645, 2016). "The patient’s father with a known history of heart failure has not yet been tested for the BAG3 variant although he has been referred to a cardiologist." (PMID 39691879, 2024). "We present the case of a 34-year-old man with new-onset decompensated heart failure and left ventricular noncompaction from a BAG3 (Bcl-2 associated athanogene 3) truncating mutation." (PMID 39691879, 2024). "BAG-3 has a role in nitric oxide release and is identified in advanced heart failure." (PMID 37371652, 2023). "Three of the genes associated with heart failure had treatment cASE: FAM241A in five conditions (copper, dexamethasone, insulin, caffeine, and vitamin A); BAG3 in five conditions (dexamethasone, caffeine, vitamin A, nicotine, and aldosterone); and KLHL3 in triclosan." (PMID 33988505, 2021). "BAG3 has been reported to maintain cardiomyocyte function during proteotoxic stress and may become a target for heart failure therapy in the clinic." (PMID 34211507, 2021). "Whether CASA operates at the cardiac sarcomere, the myofilament functional impact of BAG3, and the effect of heart failure on these mechanisms are unknown." (PMID 34011988, 2021). "We found decreased myofilament localization of the co-chaperone BAG3, such as occurs in heart failure, is directly related to the Fmax decline and show that increasing BAG3 expression in heart failure restores both function and sarcomere proteostasis through CASA." (PMID 34011988, 2021). "Interestingly, increased levels of extracellular BAG3 (secreted by stressed cardiomyocytes) and of BAG3 antibodies were identified in sera of patients with heart failure." (PMID 28680391, 2017). "Thus, BAG3 appears to be an exciting new target for therapeutic intervention in patients with heart failure." (PMID 25925243, 2015). "Two seminal findings led to the recognition that BAG3 could play a substantive role in the development of or progression of heart failure." (PMID 25925243, 2015). "Furthermore, significant decreases in the level of BAG3 have been found in end-stage failing human heart and in animal models of heart failure including mice with heart failure secondary to trans-aortic banding and in pigs after myocardial infarction." (PMID 25925243, 2015).
heart failure (continued). "However, it was the finding that mutations in BAG3 were associated with the development of muscle disease in children that led investigators to propose that changes in BAG3 function could result in the development of left ventricular dysfunction and heart failure." (PMID 25925243, 2015). "Apart from monogenic disease, BAG3 levels decrease in non-genetic heart failure, which affects a vastly larger number of patients." (PMID 39744939, 2025). "Additionally, sarcomere dysfunction due to BAG3 haploinsufficiency arises despite normal sarcomere morphology, suggesting impaired sarcomere protein turnover—not structural disarray—may be the initial insult that leads to contractile dysfunction and ultimately heart failure." (PMID 34011988, 2021). "In the present study, we used 6-week-old mice to capture the early effects of BAG3 haploinsufficiency on myofilament function, rather than the general response to heart failure development." (PMID 34011988, 2021). "BAG3 functions upstream of Parkin, and BAG3 knock-down reduced PINK1/Parkin-mediated mitophagy and impaired the clearance of defective mitochondria, thus increasing levels of toxicity within the cells and subsequent cell death in the context of heart failure." (PMID 32257551, 2020).
myofibrillar myopathy (33 papers, 2011 to 2026). "The diagnosis of myofibrillar myopathy due to a variant in BAG3 was suggested by the cardiologist given the clinical presentation." (PMID 41378130, 2025). "Neuropathy was documented in cases of BAG3-associated myofibrillar myopathy, followed by the identification of BAG3 mutations in patients affected by sensorimotor neuropathy." (PMID 40757567, 2023). "Later, more than 20 different frameshift mutations with premature stop codons, missense and nonsense mutations in the BAG3 gene have been identified and associated with myofibrillar myopathy or dilated cardiomyopathy." (PMID 40757567, 2023). "A recent study exploring the pathogenic mechanism of mutations in BAG3, associated with myofibrillar myopathy (MFM), showed striking similarities." (PMID 37923706, 2023). "Another member of the BAG family, BAG3, is highly expressed in skeletal muscle cells; its mutation being associated with severe myofibrillar myopathy." (PMID 29316663, 2018). "Our findings indicate a novel function for BAG3 in inhibiting protein aggregation caused by the genetic mutation of CRYAB responsible for human myofibrillar myopathy." (PMID 21423662, 2011). "During investigations on myofibrillar myopathy caused by ablation of the bag3 gene, we identified a direct interaction between αB-crystallin and BAG3." (PMID 21423662, 2011). "Recently, a genetic mutation where Proline is mutated to Leucine at amino acid position 209 of BAG3 has been reported in patients having severe myofibrillar myopathy." (PMID 21423662, 2011). "A BAG3 null mutation in mice results in severe progressive myofibrillar myopathy." (PMID 21423662, 2011). "In addition to the fact that BAG3 mutations also causes myofibrillar myopathy it suggests the hypothesis that dysregulation of proteostasis could be a common mechanism underlying myofibrillar myopathy and DCM." (PMID 28296976, 2017). "BAG3-related myofibrillar myopathy is an exception, with clinical manifestations beginning in childhood." (PMID 41378130, 2025). "Truncating variants in TTN are strongly associated with DCM, while mutations in DSP, LMNA, MYH7, RBM20, TNNT2, BAG3, and FLNC (the latter being linked to myofibrillar myopathy) are also commonly implicated." (PMID 39857686, 2025). "Non-sarcomeric variants such as DES, FLNC, and BAG3 promote protein misfolding or aggregation, conferring adverse prognosis, as exemplified by BAG3-related myofibrillar myopathy." (PMID 41301721, 2025). "Sequestration of FLNC or BAG3 has been proposed as a mechanism for myofibrillar myopathy whereby their accumulation depletes them from the Z-disc, compromising function and structural integrity in these fibres." (PMID 37427997, 2023). "It was shown that mutated BAG3 caused DCM, leading to systolic dysfunction, HF, and myofibrillar myopathy." (PMID 34778266, 2021). "Selcen and co-workers first reported three children with myofibrillar myopathy who harbored a single allelic substitution of Leucine (Leu) for Proline (Pro) at position 209 (exon 3 of BAG3) of BAG3." (PMID 25925243, 2015). "Second, Selcen reported three children with myofibrillar myopathy who harbored a single allelic substitution of BAG3." (PMID 25925243, 2015).
myofibrillar myopathy (continued). "We anticipate that investigation of BAG3 and the two major chaperone interactions (small heat shock proteins and Hsp70/Hsc70) will reveal potential therapeutic approaches for myofibrillar myopathy and other aggregation/degenerative diseases." (PMID 21423662, 2011). "This study reveals a potential connection between BAG3 and small heat shock proteins to prevent the protein aggregation and cell death that occurs in myofibrillar myopathy." (PMID 21423662, 2011). "Two patients (patient 1 and 2) participated in an experimental trial (approved by the local ethical committee) with metformin (2 g per day), which has shown potential benefits in animal models of BAG3-related myofibrillar myopathy, though its efficacy in humans remains uncertain." (PMID 41378130, 2025). "BAG3 pathogenic variations are associated to diverse neurological and cardiovascular diseases, including isolated cardiomyopathy in adults (OMIM 613881) and myofibrillar myopathy (OMIM 612954)." (PMID 41378130, 2025). "Myofibrillar myopathy (MFM) is also caused by aggregation-prone mutations in proteins associated with the Z-disc, including αB-crystallin, SQSTM1, and BAG3, which interact with HSPB8 to mediate chaperone-assisted-selective autophagy (CASA), a process required for the maintenance of myofibrils." (PMID 28780615, 2018). "A homozygous disruption or genetic mutation of the bag3 gene causes progressive myofibrillar myopathy in mouse and human skeletal and cardiac muscle disorder while mutations in the small heat shock protein αB-crystallin gene (CRYAB) are reported to be responsible for myofibrillar myopathy." (PMID 21423662, 2011). "Importantly, the p.Trp2710Ter-induced aggregate blocks autophagy through BAG3 recruitment to the aggregate, suggesting that both BAG3 reduction and autophagy promotion as potential therapies for FLNC p.Trp2710Ter myofibrillar myopathy." (PMID 32295012, 2020). "Here the authors show that several myofibrillar myopathy causing BAG3 mutations are not impaired in Hsp70 binding, but rather impair the ADP-ATP exchange step of the Hsp70 cycle, causing the aggregation of BAG3, Hsp70 and Hsp70 clients and leading to a collapse of protein homeostasis." (PMID 30559338, 2018).
glioblastoma (25 papers, 2013 to 2025). The most malignant astrocytic tumor (WHO grade IV). "Previous research has reported that BAG3 is associated with adverse prognoses in a variety of tumors, such as pancreatic cancer, Colon Cancer, endometrioid endometrial adenocarcinoma, and glioblastoma." (PMID 38297320, 2024). "In glioblastoma cells, BAG3 interacts with heat shock protein 70 (HSP70) to limit apoptosis by preventing the pro-apoptotic protein BAX from translocating to mitochondria." (PMID 40507324, 2025). "The multidomain protein BAG3 exerts pleiotropic oncogenic functions in many tumor entities including glioblastoma (GBM)." (PMID 38655699, 2024). "In glioblastoma, BAG3 binds bax in the cytosol which prevents bax translocation to the mitochondria and thus inhibiting apoptosis." (PMID 36980278, 2023). "BAG3 depletion was also associated with decreases in the nuclear levels of phosphorylated (activated) STAT3, whereas ectopic STAT3 overexpression normalized BAG3 levels and function in the glioblastoma cells in which BAG3 had been knocked out." (PMID 36980278, 2023). "Knockdown of BAG3 resulted in recovery of sphere-forming activity in BAG3-knockdown glioblastoma cells." (PMID 36980278, 2023). "In contrast to potential evolutionary advantage and positive selection of heart protective BAG3 variation, damaging BAG3 variation tends to rarely be related to glioblastoma cells." (PMID 36980278, 2023). "Lastly, in glioblastoma stem cells having a sphere-like phenotype, BAG3 depletion decreased sphere-forming activity, SOX-2 expression, and the expression of STAT3, a master regulator of stemness." (PMID 36980278, 2023). "While Bag3 has been identified as a key prognostic indicator in several cancer types, its investigation is limited regarding glioblastoma." (PMID 36077131, 2022). "A different mechanism has been observed in glioblastoma cells, in which BAG3 is over-expressed and retains BAX protein in the cytosol, preventing its mitochondrial translocation." (PMID 29487711, 2018). "Bcl2-interacting cell death suppressor (BIS), also known as BAG3, has antiapoptotic functions and controls cellular protein quality, and it is overexpressed in human glioblastoma tissue." (PMID 28642874, 2017). "Intriguingly, it was recently reported that in glioblastoma cells the activation of selective macroautophagy by overexpressed BAG3 is dependent on its N-terminally located WW domain." (PMID 28680391, 2017). "High BAG3 levels were claimed to contribute to the maintenance of glioblastoma stem cells that are responsible for resistance to conventional chemotherapy." (PMID 28680391, 2017). "The HSP70 co-chaperone BAG3 was found to be upregulated in many human cancers of various origins, for instance in melanomas, glioblastomas, or pancreatic adenocarcinomas." (PMID 28680391, 2017). "Bcl-2-intreacting cell death suppressor (BIS; also known as BAG3) is an anti-apoptotic protein that is highly expressed in human cancers with various origins, including glioblastoma." (PMID 27145367, 2016). "BAG3 expression was increased in glioblastoma tissues, while overexpression of BAG3 resulted in a remarkable decrease in the colony formation, a tumor suppressor-like effect at the cellular level in glioblastoma." (PMID 26621836, 2016). "Our results show that knock-down of both Bag3 and Usp9X leads to a depletion of Mcl-1 protein levels in glioblastoma cells and rendered them highly sensitive to ABT263." (PMID 26008975, 2015). "Consistently, siRNA-mediated knock-down of Bag3 significantly reduced Mcl-1 levels and sensitized T98G glioblastoma cells to ABT263." (PMID 26474387, 2015).